ALB (albumin)
Diseases named in the same sentence as ALB in open-access papers (continued):
Sharing a sentence is not in itself a finding about the gene and the disease.
myonecrosis (3 papers, 2020 to 2024). "In dystrophic muscle, albumin content was associated with areas of myonecrosis." (PMID 38929159, 2024). "Together, these data support the use of plasma albumin thiol oxidation as a biomarker to track active myonecrosis in DMD." (PMID 38929159, 2024). "We also show that both plasma albumin thiol oxidation and muscle protein thiol oxidation are sensitive to two modulators of dystropathology, treadmill exercise and taurine treatment that, respectively, increase and decrease myonecrosis." (PMID 34439489, 2021). "Additionally, plasma albumin thiol oxidation correlates with plasma CK levels, a biomarker of dystropathology (myonecrosis)." (PMID 34439489, 2021). "Therefore, albumin Cys34 has the potential to be a useful plasma biomarker of inflammation and oxidative stress to track myonecrosis." (PMID 32224496, 2020).
myositis (3 papers, 2014 to 2025). "There may be additional mechanisms by which reduced ALB increases the malignancy risk in myositis." (PMID 32846794, 2020). "Advanced age, mechanics’ hands, dyspnoea, chronic cough and fever during the course of myositis, low lymphocyte count, low serum albumin level, and high D-dimer and ferritin levels before infection were prominent in patients with severe coronavirus disease." (PMID 39928605, 2025). "For studies involving DM patients only, 17 factors were analyzed (excluding five factors: fever, rapid onset of myositis, albumin, cutaneous vasculitis and anti-Jo-1 antibody)." (PMID 24713868, 2014).
necrotizing enterocolitis (3 papers, 2021 to 2025). Necrotizing enterocolitis (NEC) is a devastating disease that affects mostly the intestine of premature infants. "Regarding the short time complications of protein supplement, blood gas analysis, BUN, and albumin levels were measured weekly, and the infants were observed for signs and symptoms of necrotizing enterocolitis (NEC)." (PMID 37368944, 2023). "We hypothesized that the serum CRP/ALB ratio has a prognostic value in predicting surgery and mortality in neonates with necrotizing enterocolitis (NEC)." (PMID 33779823, 2021).
nephromegaly (3 papers, 2021 to 2025). "Renal disease was seen in several of our adult patients and we believe that the albumin/creatinine ratio is a more sensitive marker of early onset renal disease and should be routinely screened for, along with screening for tubulopathy and nephromegaly." (PMID 33977030, 2021).
nephrosclerosis (3 papers, 2016 to 2023). Hardening of the kidney due to infiltration by fibrous connective tissue (fibrosis), usually caused by renovascular diseases or chronic hypertension. "MSC treatment resulted in lower levels of ds-DNA, ANA, Scr, BUN, proteinuria, and renal sclerosis score, and MSC treatment could get a higher level of albumin." (PMID 32019582, 2020).
neurosyphilis (3 papers, 2015 to 2025). Infection of the brain or spinal cord by Treponema pallidum. "Latent class analysis, incorporating seven key variables (sex, serum TRUST titer, CSF TTs, CSF NTTs, CSF protein, albumin quotient, and IgG synthesis rate), identified optimal subtypic clustering among suspected neurosyphilis patients." (PMID 41376790, 2025). "Our data show that a pleocytosis and an elevated albumin quotient correlate with neurosyphilis." (PMID 26445822, 2015). "A neurosyphilis was correlated to a CSF pleocytosis > 5 cells/μl and to an albumin quotient >7.8 mg/dl regardless of a parallel HIV infection." (PMID 26445822, 2015).
Newcastle disease (3 papers, 2020 to 2023). A condition caused by infection by the Newcastle disease virus, which may be characterized by conjunctivitis, respiratory illness, and diarrhea. "Dietary supplementation of DETOXIZYME increased total protein, albumin, globulin, and Newcastle Disease (ND) immunity titer levels in the overall period compared to other groups." (PMID 37024623, 2023). "Interestingly, blood total protein, albumin, Newcastle disease (ND) titer, and high-density lipoprotein (HDL) cholesterol were significantly increased, while total cholesterol was decreased by the mixture of OCM and BL (p < 0.05)." (PMID 32316269, 2020). "This pilot study found that although BX increased Newcastle disease antibody potency, ALB and GLOB levels and reduced ALT levels in broiler serum, none of these reached statistically significant levels." (PMID 37057186, 2023).
Oral leukoplakia (3 papers, 2023 to 2024). A thickened white patch on the oral mucosa that cannot be rubbed off. "Changes in non-albumin proteinuria may be suggestive of a marker of leukoplakia malignancy, while how changes in apolipoprotein B contribute to oral leukoplakia still requires further study." (PMID 39239270, 2024).
paraplegia (3 papers, 2005 to 2023). Complete paralysis of the lower half of the body including both legs, often caused by damage to the spinal cord. "Replacing the CSF with albumin- or gelatin-modified artificial CSF under physiological ICP conditions (10–15 mmHg) significantly prevented the development of paraplegia (~20% paraplegic rate, groups 4-open triangles, and 5-closed squares)." (PMID 16174300, 2005). "Replacement of CSF with albumin- or gelatin-modified artificial CSF prevented paraplegia in rabbits even when the ICP was maintained at 10–15 mmHg." (PMID 16174300, 2005). "Using albumin-modified artificial CSF to replace the CSF significantly prevented paraplegia even when the ICP was maintained within the physiological range." (PMID 16174300, 2005).
porphyria (3 papers, 2022 to 2025). Porphyria is a group of diseases in which substances called porphyrins build up, negatively affecting the skin or nervous system. "However, considering the etiology of the pathology (hemolytic disorders, parasite invasion, gastric problems, or porphyria treatment), the plasma scavenging system (haptoglobin, hemopexin, and albumin) would be challenged either by the overwhelming formation of hemin and hematin." (PMID 39996728, 2025).
prion disease (3 papers, 2021 to 2025). A transmissible disease that is caused by a protein that is able to induce abnormal folding of normal cellular proteins, leading to characteristic spongiform brain changes, which are associated with neuronal loss without an inflammatory response. "Bovine serum albumin is derived from bovine herds in North America, which are free from bovine spongiform encephalopathy." (PMID 40217906, 2025).
protein losing gastroenteropathy (3 papers, 2015 to 2022). "Symptoms of Menetrier's disease are; epigastric pain, bloating, vomiting and peripheral edema in some cases due to low albumin level." (PMID 36027830, 2022).
pyogenic liver abscess (3 papers, 2020 to 2025). Single or multiple areas of PUS due to bacterial infection within the hepatic parenchyma. "In patients with pyogenic liver abscess, the GNRI presents a better predictive performance than BMI, albumin level, platelet count, prothrombin time, and hemoglobin level in mortality and all adverse outcomes." (PMID 33321867, 2020).
pyothorax (3 papers, 2021 to 2025). "Only nine out of 27 cases showed an albumin to globulin ratio (A:G) that was lower than 0.5, though more cases with such findings were expected due to inflammation in feline pyothorax." (PMID 34438744, 2021).
retinal disease (3 papers, 2021 to 2024). "Rat neuroretinas, placed on membranes with photoreceptors facing up and exposed to albumin, mimic relevant pathological features of retinal diseases associated with blood–retinal barrier dysfunction and photoreceptor cell death." (PMID 35337132, 2022). "Reportedly, VH from eyes with retinal disease had approximately three times the normal albumin concentration." (PMID 38783230, 2024).
rhabdomyolysis (3 papers, 2020 to 2022). Necrosis or disintegration of skeletal muscle often followed by myoglobinuria. "Based on a mathematical equation using serum potassium, creatinine and albumin, rhabdomyolysis patients were also classified at “high” vs. “low risk” of AKI, although the formula was only validated in patients with serum creatinine < 265 μmol/L." (PMID 32998294, 2020). "Copper is then bound rapidly from the gastrointestinal tract by carrier proteins, ceruloplasmin and albumin, and transported to the liver and other tissues, where it can cause hepatotoxicity, methemoglobinemia and rhabdomyolysis." (PMID 32926692, 2020). "Novel MCO membrane might represent the optimal mode of treatment of severe rhabdomyolysis-associated AKI, as it allows for efficient removal of myoglobin, avoids albumin supplementation and is associated with lower costs." (PMID 35340002, 2022).
selenium deficiency (3 papers, 2005 to 2021). A nutritional deficiency disease resulting from inadequate selenium levels in the body, which can lead to impaired function of selenoproteins essential for antioxidant defense and thyroid hormone metabolism. "Maternal selenium deficiency did not impact the urinary concentrations of sodium, potassium, chloride, glucose, urea, albumin, creatinine, or total protein." (PMID 33769708, 2021).
septic arthritis (3 papers, 2021 to 2025). "Then, we found that CRP > 130 mg/L, albumin < 3.4 g/dL and preoperative antibiotics days > 8 predisposed the coexisting infections of infectious spondylitis and septic arthritis." (PMID 34830626, 2021). "Multivariable logistic regression identified normal serum albumin levels, severe ultrasound-detected bone erosion, and imaging evidence of joint surface destruction as significant predictors of chronic occult infectious arthritis." (PMID 40943972, 2025). "In our current finding, CRP increases and ALB decreases in children with septic arthritis." (PMID 38293658, 2023). "Overall, Alb may reflect the inflammatory status of the disease, but its utility in distinguishing chronic occult infectious arthritis from undifferentiated oligoarthritis requires longitudinal data and future work to assess the stability of albumin across the disease course and treatment response." (PMID 40943972, 2025). "This study aimed to investigate the relationship between the ratio of c-reactive protein to albumin (CAR) and pediatric septic arthritis (PSA)." (PMID 38293658, 2023).
Sjögren's syndrome (3 papers, 2006 to 2023). "Additionally, while the exact mechanism is not well understood, there has been recent research indicating that low albumin levels predict PPF in Sjögren's syndrome-related interstitial pneumonia patients, probably reflecting ongoing inflammation." (PMID 37831431, 2023).
stomatitis (3 papers, 2011 to 2025). Inflammation of the oral mucosa due to local or systemic factors. "Stomatitis often reduces food intake, lowering albumin levels and further increasing the risk of stomatitis, thus creating a vicious cycle." (PMID 40988098, 2025). "Furthermore, the decrease in albumin levels is likely due to stomatitis-induced decreased appetite; therefore, stomatitis management is also important for maintaining nutritional status." (PMID 40988098, 2025). "Stomatitis is more likely to occur if albumin levels drop, creating a vicious cycle." (PMID 40988098, 2025).
TB meningitis (3 papers, 2013 to 2021). "GFAP and the albumin index were significantly higher in bacterial and tuberculosis meningitis groups, whereas total tau was elevated in the Japanese encephalitis virus infection group." (PMID 33115334, 2021). "The present study shows that serum albumin can be used as a low-cost prognostic factor in HIV-related tuberculous meningitis." (PMID 23997952, 2013).
tubulointerstitial nephritis (3 papers, 2025). "Based on Sri Lankan criteria, heat stress nephropathy was defined by albumin-creatinine ratio ≥ 30 mg/g, no known CKD causes, urine specific gravity ≥ 1.03, and signs of tubulointerstitial nephritis." (PMID 41141547, 2025).
type IV hypersensitivity reaction (3 papers, 2018 to 2021). "Although nickel-induced allergic contact dermatitis has been associated with a type IV hypersensitivity reaction, several case reports have described specific IgE antibodies against nickel and nickel–albumin conjugates." (PMID 34209104, 2021). "We propose that the Ti-albumin antigens act as haptens typical for a type IV hypersensitivity reaction, but this must be further investigated in a mechanistic study." (PMID 29642398, 2018).
upper respiratory tract infection (3 papers, 2018 to 2025). "There is often a prodromal upper respiratory tract infection, CSF albumin-cytologic dissociation, and serum anti-ganglioside antibodies." (PMID 39997655, 2025).
urinary schistosomiasis (3 papers, 2009 to 2021). A bladder infection that occurs as a manifetation of a systemic infection with one or more species of the parasitic worms of the Schistosoma type; this can progress to bladder cancer in time. "We therefore aimed to determine associations between excreted urine-albumin, as measured using a HemoCue photometer, and UTPs, as detected by ultrasonography, in children and adults from an urinary schistosomiasis endemic area in Zanzibar." (PMID 19806223, 2009). "Also, urinary schistosomiasis has been reported in some studies to cause urinary tract pathology from chronic bladder lesion caused by deposition of schistosome eggs marked by ultrasonographic lesions and high urine albumin to creatinine ratio." (PMID 31211789, 2019). "Proteinuria had the second higher concordance, this could be the effect of S. haematobium eggs on the glomeruli leading to excretion of albumin in urine thereby indicating infection with urinary schistosomiasis." (PMID 37359201, 2021).
urticaria (3 papers, 2009 to 2022). A vascular reaction of the skin characterized by erythema and wheal formation due to localized increase of vascular permeability. "Clinical symptoms in dogs receiving non-canine albumin ranged from edema (facial, distal limbs), urticaria, vomiting, and diarrhea to severe shock-like reactions (hypotension, collapse)." (PMID 23870652, 2013).
uveal melanoma (3 papers, 2023 to 2025). A melanoma derived from melanocytes of the uveal tract. "While free AZD8055 is impossible to administer intravenously due to its hydrophilicity, the albumin-based NPs aided its systemic administration in mice and its reach to uveal melanoma (Mel202) cells." (PMID 40227824, 2025).
ventricular fibrillation (3 papers, 2019 to 2023). A disorder characterized by an electrocardiographic finding of a rapid grossly irregular ventricular rhythm with marked variability in QRS cycle length, morphology, and amplitude. "Moreover, nonsurvivors had higher levels of BNP and aspartate aminotransferase (AST) and lower levels of albumin than survivors and were more likely to develop cardiogenic shock, ventricular fibrillation (VF) or ventricular tachycardia (VT), ARF and UGIB than survivors." (PMID 31000758, 2019).
ventricular septal defect (3 papers, 2021 to 2022). The presence of a defect (opening) in the septum that separates the two ventricles of the heart. "At multivariable linear regression analysis only haemoglobin and albumin featuring an association with spontaneous closure of perimembranous ventricular septal defect (p < 0.005 and p < 0.02, respectively)." (PMID 34682146, 2021). "This study aimed to assess the impact of a series of laboratory parameters on spontaneous full healing of perimembranous ventricular septal defect: haemoglobin, haematocrit, foetal haemoglobin, peripheral oxygen saturation, iron, transferrin, ferritin, and albumin blood levels." (PMID 34682146, 2021). "Low albumin levels are likely caused by acute and/or chronic heart disease due to systolic or diastolic left ventricular dysfunction, which are not uncommon in ventricular septal defect patients." (PMID 34682146, 2021). "In fact, preoperatively, surfactant-specific protein SP-B is increased in all CHD, while MPO (neutrophil) activity is decreased only in tetralogy of Fallot, and albumin and surfactant-specific protein-A are increased only in ASD and ventricular septal defect, compared to age-matched controls." (PMID 35333340, 2022).
visceral leishmaniasis (3 papers, 2014 to 2025). A severe form of leishmaniasis characterized by irregular bouts of fever, substantial weight loss, swelling of the spleen and liver, and anemia (which may be serious). "MDP conjugated with the neoglycoprotein mannosyl human serum albumin (mannose-HSA), in a murine model of visceral leishmaniasis, strongly reduced splenic parasite burden, whereas free MDP at a similar dose had very little effect." (PMID 24927796, 2014).
vitamin A deficiency (3 papers, 2011 to 2022). Deficiency of vitamin A due to malnutrition, malabsorption, or dietary lack. "Concretely, 23/36 (63.9%) of the women for whom we had an albumin measurement had vitamin A deficiency, 19/44 (43.2%) had vitamin C deficiency, and 5/37 (13.5%) had vitamin E deficiency." (PMID 36235668, 2022). "This might be attributable to the association of reduced albumin and prealbumin with vitamin A deficiency." (PMID 28241813, 2017).
xerostomia (3 papers, 2018 to 2023). Dryness of the mouth resulting from reduced salivary secretion. "Saliva samples were taken before and after the MD was used on a 68-year-old patient suffering from post-irradiation xerostomia, and albumin and total protein were analyzed." (PMID 37763766, 2023). "SSS showed higher total ESSPRI score and higher prevalence of xerostomia and low C3, C4 levels with more liver, articular involvement and saliva gland atrophy, while pSS had a higher level of albumin." (PMID 29703151, 2018).
abdominal hernias (2 papers, 2025). "In contrast, PDV (P < 0.01), PDM (P < 0.01), serum albumin level (P < 0.01), and age (P < 0.01) were found to be significantly associated with the development of abdominal wall hernia during peritoneal dialysis." (PMID 41446859, 2025).
Achalasia (2 papers, 2019 to 2023). A disorder of esophageal motility characterized by the inability of the lower esophageal sphincter to relax during swallowing and by inadequate or lacking peristalsis in the lower half of the body of the esophagus. "Although our results showed macronutrient deficiency (low serum protein and albumin) among patients with achalasia, micronutrients (iron, Hb, and calcium) were comparable." (PMID 31832546, 2019). "Patients with achalasia had lower total serum protein and albumin than healthy controls." (PMID 31832546, 2019).
acne (2 papers, 2023 to 2024). An inflammatory process of the sebaceous glands which is characterized by comedones, nodules, papules and/or pustules on the skin. "The area under the curve (AUC) value of the CRP/albumin ratio in the receiver operating characteristic (ROC) analysis between the acne and control groups was 0.660, and its cut-off value was found to be 0.236 with 68.6% sensitivity and 68.9% specificity." (PMID 37750127, 2023). "Based on the PPI network analysis and topology algorithm in Cytoscape software, TNF, GAPDH, IL6, Albumin (ALB), and protein kinase 1 (AKT1) are considered to be the core target proteins for the treatment of acne." (PMID 39029003, 2024). "CRP/albumin ratio and MCR may serve as inflammatory markers that can be used to monitor the severity of acne vulgaris." (PMID 37750127, 2023).
acute tubular necrosis (2 papers, 2022 to 2023). "Considering the low creatinine clearance and elevated urinary albumin/serum creatinine ratio, urinary N-acetyl-β-d-glucosaminidase level, and β2-microglobulin level, the patient was further diagnosed with AKI (in other words, acute tubular necrosis)." (PMID 37715272, 2023).
Adrenal insufficiency (2 papers, 2017 to 2022). Insufficient production of steroid hormones (primarily cortisol) by the adrenal glands. "If blood albumin is normal (≥2.5 gr/dl), serum cortisol less than 10 μg/dl is considered as adrenal insufficiency." (PMID 35251166, 2022). "However, if the blood albumin level is less than 2.5 gr/dl, adrenal insufficiency is diagnosed when the serum cortisol level is less than 8 μg/dl." (PMID 35251166, 2022).